CD44 (CD44 molecule (IN blood group))
Diseases named in the same sentence as CD44 in open-access papers (continued):
Sharing a sentence is not in itself a finding about the gene and the disease.
lung adenocarcinoma (continued). "Data from the present study suggest that CD44 SNPs may help to predict cancer susceptibility and tumor growth in male patients with lung adenocarcinoma." (PMID 32344833, 2020). "The data indicated that the CD44 rs11821102 G/A polymorphism might influence unique microRNA, thereby altering specific CD44 mRNA subtypes in male patients with lung adenocarcinoma harboring the EGFR L858R mutation." (PMID 32344833, 2020). "Therefore, in the present study, we explored the association between CD44 and PD-L1 in lung adenocarcinoma." (PMID 33372595, 2020). "Positive association between CD44 and PD-L1 were found in lung adenocarcinoma patients." (PMID 33372595, 2020). "However, adenocarcinoma of the lung is usually accompanied by a morphological decrease in and subsequent loss of CD44." (PMID 21819617, 2011). "Moreover, it needs to conduct further research on larger cohorts, different races and even the international multicenters to investigate and confirm the association between these CD44 SNPs and clinicopathological characteristics patients with lung adenocarcinoma." (PMID 32344833, 2020). "Therefore, the CD44 rs713330 polymorphism may be associated with the primary tumor size and invasion of lung adenocarcinoma in male patients, particularly those with wild-type EGFR." (PMID 32344833, 2020). "Moreover, we analyzed the association between PD-L1 and CD44 in lung adenocarcinoma." (PMID 33372595, 2020). "This study aimed to develop high-molecular-weight hyaluronic acid-modified, cisplatin-loaded mesoporous silica nanoparticles (HA-MSN-CDDP) to selectively target CD44-overexpressing lung adenocarcinoma cells." (PMID 41754914, 2026). "A recent research study demonstrated that pericyte-like cells derived from CD44+ lung adenocarcinoma stem cell populations have a strong brain metastasis-initiating capacity." (PMID 41356185, 2026). "Mechanistically, TNFAIP6 interacted with CD44 in lung adenocarcinoma cells, leading to increased extracellular availability of secreted phosphoprotein 1 (SPP1) within the TIME and the subsequent promotion of NETosis." (PMID 41899624, 2026). "CD44+ stem cells in lung adenocarcinoma (LADC) differentiate into pericyte‐like cells (CD‐pericytes), which exhibit significantly increased transendothelial migration." (PMID 41245887, 2025). "The findings revealed that CD44 expression is up-regulated in KRAS-induced lung adenocarcinomas and that CD44 mediates KRAS-dependent MAPK activation and cell proliferation." (PMID 38672650, 2024). "CD44, which has been widely regarded as a CSCs marker in several cancers, has also been shown to have more prominent stemness features in CD44+ subpopulations of lung adenocarcinoma." (PMID 39457544, 2024). "HA activation of CD44 is known to exert significant effects on cancer metastasis of a variety of tumor types including lung adenocarcinoma, in part, by potentiating the activation of PI3K, AKT, and nuclear localization of NFκB." (PMID 36766747, 2023). "In clinical samples, the co-expression of TGF-β1 and CXCR7 positively correlates with CD44 levels in advanced lung adenocarcinoma, confirming the involvement of CXCL12 in maintaining stem-like properties of NSCLC cells." (PMID 38139154, 2023). "IDH1 positively correlates with CD44 and reduced glutathione in lung adenocarcinomas, suggesting a positive effect of IDH1 on tumor growth." (PMID 36497259, 2022). "CD44 expression is positively correlated with immune cells, and lung adenocarcinoma patients with higher CD44 levels have worse overall survival." (PMID 36316684, 2022). "CD44 was found to critically contribute to activating the oncogenic KRAS signalling pathway through the MAPK pathway in lung adenocarcinoma cell lines, hence promoting tumour cell proliferation and survival." (PMID 34944493, 2021).
lung adenocarcinoma (continued). "These processes contributes to the growth of lung cancer spheres via SOX9-mediated stem-like properties, suggesting that HDAC10-TGF-β-SOX9-SLUG/CD44 axis plays an essential role in lung adenocarcinoma." (PMID 33997894, 2021). "Results have shown that lung adenocarcinoma patients with low CD44 expression had significantly prolonged OS than those with high expression (P = 0.002)." (PMID 33372595, 2020). "In the present study, we have found that CD44 was positively correlated with PD-L1 expression (r = 0.46, P = 2.86e−28) in lung adenocarcinoma using TIMER database." (PMID 33372595, 2020). "To validate the correlation between CD44 and PD-L1 in lung adenocarcinoma patients with different stages, we presented representative images using tumor tissues from lung adenocarcinoma patients with stage I and stage III by immunohistochemistry." (PMID 33372595, 2020). "To further ascertain the impact of tumor stage on CD44 expression, we analyzed CD44 expression in lung adenocarcinoma patients with stage I and stage II/III." (PMID 33372595, 2020). "In the current study, B cell, CD8+ T cell, CD4+ T cell, macrophage, neutrophil and dendritic cell (DC) were all analyzed for their correlation with CSC, as reflected by CD44, in lung adenocarcinoma." (PMID 33372595, 2020). "The result also showed that lung adenocarcinoma patients with relatively low CD44 expression had improved OS compared with those with high expression (P < 0.001)." (PMID 33372595, 2020). "We further evaluated the prognostic role of CD44 in patients with lung adenocarcinoma both using Kaplan–Meier plotter and validated in our patient cohort." (PMID 33372595, 2020). "We further analyzed the association between various forms of CD44 copy number and immune cells B cell, CD8+ T cell, CD4+ T cell, macrophage, neutrophil and dendritic cell infiltration in lung adenocarcinoma." (PMID 33372595, 2020). "We observed that the CD44 rs713330 T/C polymorphism was highly associated with primary tumor size and invasion (AJCC “T” classification) in male patients with lung adenocarcinoma." (PMID 32344833, 2020). "Studies have also determined the functional role of CD44 in cytokine production and secretion and deemed it a typical surface marker in lung adenocarcinoma." (PMID 33372595, 2020). "The associations among CD44 SNPs, EGFR mutations, and the clinicopathological characteristics of lung adenocarcinoma are also evaluated." (PMID 32344833, 2020). "Previously, we identified that elevated expression of PKM2 is involved in cell proliferation and tumour formation in CD44+ A549 lung adenocarcinoma stem cells." (PMID 30925904, 2019). "More importantly, we found that enhanced PKM2 expression contributes to stress resistance and therapeutic resistance in CD44+ A549 lung adenocarcinoma stem cells, suggesting PKM2 as a potential target for lung adenocarcinoma therapy." (PMID 30925904, 2019). "The expression of EMT-related proteins including cytokeratin, E-cadherin, TTF-1, β-catenin, vimentin, Snail, Twist, CD44 was evaluated by immunohistochemistry using a tissue array method in the lung adenocarcinoma tissues of 95 patients." (PMID 23706092, 2013). "In this study, using a tissue array method, we investigated the expression of known EMT-related proteins including cytokeratin, E-cadherin, TTF-1, β-catenin, vimentin, Snail, Twist, CD44 in lung adenocarcinoma patients’ samples." (PMID 23706092, 2013). "Furthermore, CD44+ primary lung adenocarcinoma cells show a clear EMT induction and have higher tumorigenic potential in nude mouse xenografts compared to CD44- cells." (PMID 38139154, 2023). "The analysis of samples from patients with lung adenocarcinoma shows that CD44 levels are higher in tumors than in normal lung tissue, correlate with the expression of EMT markers (inversely with E-cadherin and directly with Snail and Twist), and predict the likelihood of metastasis." (PMID 38139154, 2023).
lung adenocarcinoma (continued). "Thus, targeting SPP1-related signaling pathways such as the SPP1/CD44 axis is a promising approach for the treatment of lung adenocarcinoma." (PMID 37190178, 2023). "Furthermore, the role of CD44 in predicting OS in patients with lung adenocarcinoma was also analyzed." (PMID 33372595, 2020). "Data from the present study suggest that CD44 SNPs may be a useful prediction marker for male patients with lung adenocarcinoma." (PMID 32344833, 2020). "In summary, these results demonstrate that CD44 was associated with PD-L1 and infiltration of immune cells, and was a negative prognostic factor for predicting worsened OS in lung adenocarcinoma." (PMID 33372595, 2020). "In the current study, we investigated the relationship between CD44 polymorphisms and the susceptibility to lung adenocarcinoma with or without epidermal growth factor receptor (EGFR) gene mutations." (PMID 32344833, 2020). "In the present study, we aim to clarify the relationship between CD44 polymorphisms and susceptibility to lung adenocarcinoma with or without EGFR mutations." (PMID 32344833, 2020). "We therefore speculate that lung adenocarcinoma patients with higher CD44 expression may be surrounded by robust immune cell infiltration whereas these surrounding cells do not exert proper anti-tumor effects against CSC." (PMID 33372595, 2020). "Together, these data suggest that increased CD44 expression was correlated with the poor OS among lung adenocarcinoma patients, and the CD44 expression could serve as a useful biomarker for predicting prognosis among patients with lung adenocarcinoma." (PMID 33372595, 2020). "We used X-tile software to calculate the most efficient cut-off value of CD44 expression that could most significantly distinguish the outcome of patients with lung adenocarcinoma." (PMID 33372595, 2020). "The CD44 antigen (CD44), depicted in the tumor invasion network was selected for orthogonal cross-validation because of its well-described role in tumorigenesis and invasion of lung adenocarcinoma driven by oncogenic KRas mutants." (PMID 29899869, 2018). "Finally, we analyzed the role of CD44 in affecting OS in lung adenocarcinoma patients." (PMID 33372595, 2020). "Besides, it has to be noted that although CD44 was linked with increased infiltration of immune cells whereas found to be a negative biomarker associated with worsened OS in lung adenocarcinoma patients." (PMID 33372595, 2020). "In lung adenocarcinoma, EDH1 interaction with CD44 was shown to promote CSCs‐like traits, EMT, and metastasis via inhibition of the Hippo pathway." (PMID 38783892, 2024). "Studies in lung adenocarcinoma patients show increased expression levels of wild-type IDH1, CD44, and reduced glutathione." (PMID 36497259, 2022). "Immunohistochemical (IHC) staining performed on 12 lung adenocarcinoma (LA) tissue samples showed protein expression of OCT4, NANOG, SOX2, KLF4 and c-MYC, and the CSC marker CD44." (PMID 34685477, 2021). "TGFβ promoted the cleavage of CD44 and formation of the CD44 TM-ICD domain in a time-dependent manner in the lung adenocarcinoma A549 cell line, as did several other growth factors." (PMID 33804427, 2021). "In lung adenocarcinoma, SOX9, SLUG and CD44 are activated by the down-regulation of HDAC10 and stimulation of TGF-β, which mediates CSC-related cancer progression." (PMID 33997894, 2021). "We have previously shown that SRGN is frequently overexpressed in lung adenocarcinomas, and functions in promoting NSCLC cell migration, invasion and stemness in a CD44-dependent manner." (PMID 31898491, 2020). "In the present study, we have found lower expression of CD44, a surface marker of CSC, in lung adenocarcinoma." (PMID 33372595, 2020). "These networks contain human-derived N-glycoproteins with an already-established linkage/role in lung adenocarcinoma signaling (e.g., CD44, CD147) and proteins whose relevance to the biology of lung adenocarcinoma is less clear (e.g., CDH17)." (PMID 29899869, 2018).
lung adenocarcinoma (continued). "However, CD44 expression apparently decreased within bladder urothelial carcinoma (BLCA), lung adenocarcinoma (LUAD), prostate adenocarcinoma (PRAD), and uterine corpus endometrial carcinoma (UCEC) tissues." (PMID 38590654, 2024). "CD44 positive cells from lung adenocarcinoma patients, compared to CD44 negative cells, have higher metastatic ability mediated by the Wnt/β–catenin–FoxM1–twist pathway." (PMID 34439211, 2021). "In summary, we have demonstrated that CD44 is positively correlated with PD-L1 expression, immune cells infiltration and serves as a negative prognostic biomarker in lung adenocarcinoma." (PMID 33372595, 2020). "We have demonstrated that CD44 is positively correlated with PD-L1 expression, immune cells infiltration and serves as a negative prognostic biomarker in lung adenocarcinoma." (PMID 33372595, 2020). "We further examined the expression of CD44 both in tumor and nontumor tissues in lung adenocarcinoma patients." (PMID 33372595, 2020). "Interestingly, although lower CD44 expression was found in tumor compared with nontumor tissues, lung adenocarcinoma patients with higher CD44 expression were found to have worsened survival." (PMID 33372595, 2020). "We isolated putative lung CSCs from lung adenocarcinoma cells (A549 and H2170) and normal stem cells from normal bronchial epithelial cells (PHBEC) on the basis of positive expression of stem cell surface markers (CD166, CD44, and EpCAM) using fluorescence-activated cell sorting." (PMID 25881239, 2015). "Although CD44 and CD24 were not concluded as the optimal cancer stem cell markers for lung adenocarcinoma cells, CD44+CD24−/lo A549 cells also showed mildly enhanced anchorage-independent in vitro self-renewal." (PMID 35883497, 2022). "Immunocytochemical staining of the respective CSC markers in the well-established lung adenocarcinoma-derived cell line LXF-289 revealed no expression for cancer stem cell markers CD133 and Nestin and only low expression of CD44 in comparison to LCSC-like cells." (PMID 33925297, 2021). "Additionally, immunocytochemical investigation of the well-established lung adenocarcinoma cell line LXF-289 revealed no expression for CD133 and Nestin and lower expression of CD44, underpinning the presence of a CSC phenotype in the here-presented BKZ cell populations." (PMID 33925297, 2021).
acute myeloid leukemia (55 papers, 2010 to 2025). Acute myeloid leukemia (AML) is a group of neoplasms arising from precursor cells committed to the myeloid cell-line differentiation. "Furthermore, increased transcription of CD44 mRNA was observed in human acute myeloid leukemia (AML) patients with FLT3 or DNMT3A mutations through the suppression of CpG islands methylation in the promoter." (PMID 37504249, 2023). "Human acute myeloid leukemia (AML) cells also express high levels of CD44 mRNA due to the suppression of methylation of the CpG islands in the promoter." (PMID 37489367, 2023). "Encouragingly, MAPK3 and CD44, as hub genes, were not only enriched in “ferroptosis” and “acute myeloid leukemia” pathways but also significantly correlated with prognosis and immune cell infiltration in AML patients." (PMID 36612069, 2022). "CD44v6 is an isoform of the hyaluronate receptor CD44 expressed in MM, acute myeloid leukemia and solid tumors, where it plays a role in tumor growth and dissemination." (PMID 32850376, 2020). "Overexpression of CD44 isoforms has been reported in hematopoietic malignancies such as non-Hodgkin’s lymphoma, myeloma, and chronic and acute myeloid leukemia." (PMID 32742599, 2020). "Bone marrow stroma has been shown to protect acute myeloid leukemia cells from inhibition by an anti-CD44 antibody in part via PI3K/Akt signaling." (PMID 29930760, 2018). "An anti-CD44 mAb A3D8, which binds to CD44 at the non- hyaluronic acid binding region, has also been observed to induce apoptosis in acute myeloid leukemia cells by inducing lipid raft clustering." (PMID 29423071, 2018). "CD44 targeting is used in the treatment of acute myeloid leukemia (AML), CD24 targeting is for the treatment of colon and pancreatic cancer and CD133 is targeted for the treatment of hepatocellular and gastric cancer." (PMID 25071581, 2014). "Anti-CD44 antibodies are found to induce the differentiation of acute myeloid leukemia (AML) stem cells." (PMID 23527117, 2013). "In addition, human acute myeloid leukemia (AML) cells have been shown to express high levels of CD44 mRNA as a result of reduced CpG island methylation within the promoter region." (PMID 41369362, 2025). "In acute myeloid leukemia, the administration of a monoclonal antibody against CD44 markedly reduced the repopulation of leukemic stem cells in vivo; however, this effect was due to the inhibition of proper homing of leukemic stem cells to microenvironmental niches." (PMID 37108495, 2023). "In addition, the anti-CD44 mAb A3D8 enhanced apoptosis in acute myeloid leukaemia cells through caspase-8 activation by binding to CD44s protein." (PMID 34944493, 2021). "Moreover, anti-CD44 monoclonal antibodies have also shown the promising potential of eradicating acute myeloid leukemia stem cells by inhibiting acute myeloid leukemia stem cell homing." (PMID 32347296, 2020). "Previous studies have shown that anti-CD44 monoclonal antibodies inhibit the proliferation and reverse the differentiation arrest of acute myeloid leukemia cell lines and primary acute myeloid leukemia cells by increasing the expression level and stability of the p27 protein." (PMID 32347296, 2020). "CD44, the transmembrane protein that is the receptor for matrix components such as hyaluronic acid selectin, collagen, and osteopontin, has been proven to help treat acute myeloid leukemia (AML) by inhibiting tumor proliferation, and increasing apoptosis." (PMID 31709180, 2019). "Thus, at least three adhesion mechanisms, CXCR4/SDF1 (CXCL12), VLA-4/VCAM-1 or fibronectin, and CD44/ligand, function in acute myeloid leukemia migration, retention, and survival." (PMID 22346731, 2012). "Treatment with anti-CD44 demonstrated inhibition of tumor proliferation and increased apoptosis in acute myeloid leukemia (AML)." (PMID 37784157, 2023). "CD44 was suggested as a marker on acute myeloid leukemia (AML) leukemic stem cells (LSCs) [reviewed in Ref." (PMID 25904917, 2015).